ZEB1 (zinc finger E-box binding homeobox 1)
Diseases named in the same sentence as ZEB1 in open-access papers (continued):
Sharing a sentence is not in itself a finding about the gene and the disease.
tumor (continued). "For example, transcription factor ZEB1 can stimulate EMT-mediated tumor metastasis and high transcript levels of ZEB1 can sensitize cancer cells to ferroptosis through promoting the increase of PPARγ, a major regulator of lipid metabolism in liver." (PMID 35155451, 2021). "High zinc finger E-box binding homeobox 1 levels in mesenchymal tumor cells repressed p21, leading to perturbed CDK4 pathway activity." (PMID 34309585, 2021). "In hypoxic conditions, Twist is overexpressed and targets downstream platelet-derived growth factor α (PDGFα), while ZEB1 supports tumor progression through EMT induction and VM processes." (PMID 34830097, 2021). "Agradual decrease in Snail expression in tumor cells during colonization, whichis due to inhibition by microRNAs, causes MET induction: in particular, miR-34and miR-200 inhibit Snail and ZEB1/2 transcription factors." (PMID 33959388, 2021). "Tumor regions with high nuclear ZEB1 corresponded to lower levels of nuclear p21 in KP and KM tumors, as compared with Kras tumors alone." (PMID 34309585, 2021). "Zinc-finger E-box-binding homeobox 1 (ZEB1) has been characterized as a crucial driver of tumor invasion, distant metastasis, drug resistance, and radioresistance by inducing the EMT in tumor epithelial cells." (PMID 33649471, 2021). "The miR-200 family (miR-200a, miR-200b, miR-200c, miR-429, and miR-141) is a well-known tumor suppressor that inhibits EMT by targeting ZEB1 and ZEB2 in a wide range of cancers." (PMID 33898432, 2021). "The reduction of cancer cell-specific Zeb1 protein expression was confirmed through immunolabeling of the primary tumor in both the KPPC;ZF+ and the KPPC; Zeb1cKO as well as quantified with the co-expression of mesenchymal markers and the lineage tracer YFP." (PMID 33852841, 2021). "Up‐regulation of ZEB1 has been found in a variety of tumours and positively correlated with the degree of malignancy and poor prognosis." (PMID 33960640, 2021). "After docetaxel therapy (V2), high ZEB1 expression was observed mainly in those patients with early tumour progression (Fisher test, p = 0.02) or death (Fisher test, p = 0.04)." (PMID 33635497, 2021). "Then, the IHC staining was applied to detect the protein expression of proliferation marker Ki67 and ZEB1 in tumor tissues from nude mice." (PMID 33902589, 2021). "Previously, we and others reported that 3′ UTRs of Snail and Zeb1 contain tumor suppressive miR binding sites miR-34a and miR-200, respectively." (PMID 34502497, 2021). "ZEB1 has been identified as a pleiotropic transcription factor that can dominate cell fate and regulate tumor malignant progression in various cancers." (PMID 34493213, 2021). "Recently, a growing amount of evidence has suggested that ZEB1 plays a central role in epithelial-to-mesenchymal transition (EMT) during tumor metastasis 11-13." (PMID 34234851, 2021). "IHC studies showed that the number of Zeb1+ tumor cells is significantly increased at the invasive front of tumors from patients treated with DPP-4i." (PMID 36860286, 2021). "To confirm that LINC01303 participated in tumor developmental process through miR-429/ZEB1 axis, we carried out cotransfection experiments." (PMID 34912458, 2021). "Recent findings suggest that ZEB1 is one of the most critical factors regulating tumor cell plasticity." (PMID 34462429, 2021). "ZEB2 was elevated in ascitic cells, while the changes in ZEB1, Snail and Twist1 in ascites and primary tumours were mild." (PMID 34211089, 2021). "Recent studies have demonstrated that tumor suppressive miR-34a and miR-200 repress Snail and Zeb1 expression via direct targeting of their respective UTRs." (PMID 34502497, 2021).
tumor (continued). "Increased expression of CDH2, CTSB, ACTA2, MMP2 and ZEB1 was associated with increased myometrial invasion, and expression of CTSB and MMP9 was significantly associated with tumor recurrence." (PMID 34936030, 2021). "The EMT-activator ZEB1 is highly relevant to the regulation of the ubiquitination process, tumor invasion, and metastasis in cancers." (PMID 34635635, 2021). "IHC revealed that the number of Zeb1+ tumor cells increased in tumors from DPP-4i–treated patients than tumors from nonusers (P < 0.01)." (PMID 36860286, 2021). "The activation of the ovarian TAM pro-tumor phenotype requires the expression of zinc finger E-box binding homeobox 1 (ZEB1), a driver of the epithelial-mesenchymal transition (EMT), and involves direct crosstalk with tumor cells." (PMID 34359708, 2021). "The results showed that the overexpression of VIM-AS1 dramatically facilitated Ki67 and ZEB1 levels, while overexpression of miR-655 notably inhibited Ki67 and ZEB1 levels tumor tissues." (PMID 33902589, 2021). "Accordingly, a recent study revealed that miR-200 removal in an insulinoma mouse model, as well as the depletion of miR-200 sites in endogenous Zeb1, caused beta-cell dedifferentiation, EMT initiation, and tumor invasion." (PMID 34439740, 2021). "Several studies show the tumor-suppressive role of miR-200b in PC by targeting different genes, e.g., ZEB1, ZEB2 and Bmi-1." (PMID 33331954, 2021). "miR-643 has been reported as a tumour suppressor in osteosarcoma cells, which can target ZEB1 and reduce tumour progression." (PMID 34071504, 2021). "Based on the data obtained from the vitro experiments, we further studied the effects of ZEB1 on tumour growth in vivo." (PMID 33960640, 2021). "This reactive astrogliosis has been noted to contribute to tumor cell infiltration through the activation of zinc finger E-box-binding homeobox 1 (ZEB1), an epithelial–mesenchymal transition (EMT) transcription factor." (PMID 34571905, 2021). "Upon orthotopic transplantation of the AKP-Z organoids and subsequent establishment of the primary tumor in the caecum, mice were administered doxycycline for 1 week in the drinking water to induce Zeb1 expression." (PMID 34036938, 2021). "Zinc-finger E-box-binding homeobox 1 (ZEB1) is a crucial inducer of epithelial-to-mesenchymal transition (EMT) to promote tumor proliferation and metastasis, but the regulatory mechanism of ZEB1 stability in HCC remains enigmatic." (PMID 33649471, 2021). "The results showed significantly higher values of ZEB1 expression in GC tissues compared to adjacent non-tumor tissues and normal tissues (median of fold change expression, 17.95 vs. 4.23, p=0.009; 17.95 vs. 2.81, p<0.001, respectively)." (PMID 32153739, 2020). "In another instance, it has been reported that ZEB1 is an efficient factor in elevating the malignancy of tumor cells, through the induction of PD-L1 expression to enhance the levels of CD8+ T-cell immunosuppression and cancer metastasis." (PMID 32664703, 2020). "Increasing evidence suggests that ZEB1 stimulates tumor cells with mesenchymal traits and promotes multidrug resistance, proliferation, and metastasis, indicating the importance of ZEB1-induced EMT in cancer development." (PMID 32014049, 2020). "Dysregulation of ZEB1 and ZEB2 have been involved in tumor progression associated with the development of mesenchymal phenotype, stem-like properties, metastasis, and resistance to therapeutic agents." (PMID 32987716, 2020). "High expression of ZEB1 in tumor-budding and stromal cells was correlated with high peritumoral invasion." (PMID 32781778, 2020). "On the other hand, HIF can promote the migration and invasion of tumor cells through regulating the related transcription factors (Snail, Slug, Twist, ZEB1, SIP1, etc.)." (PMID 32377312, 2020). "miR-200c, a known tumor suppressor miRNA, also suppresses invasion by directly targeting ZEB1 and ZEB2." (PMID 32293453, 2020).
tumor (continued). "GSEA analysis also confirmed that loss of Zeb1 in PyMT;Zeb1cKO tumor cells was negatively enriched among genes associated with angiogenesis and VEGF-related signatures compared with that in PyMT tumor cells." (PMID 33046710, 2020). "Depletion of Zeb1 disrupts this positive feedback loop in the tumor perivascular niche, which eventually lessens tumor initiation and progression in vivo and in vitro." (PMID 33046710, 2020). "ZEB1 is a transcription factor that promotes tumor invasion and metastatic spread by inducing epithelial-mesenchymal transition and is implicated in gemcitabine-based resistance." (PMID 33266052, 2020). "In the present study, we provide further evidence that endothelial cells within the tumor function as a CSC niche by directly providing Jag1 to the Notch1 receptors expressed in breast CSCs to elevate Zeb1 expression." (PMID 33046710, 2020). "The expression level of miRNAs was also studied, since the miR200 family members (miR200a, miR200b, miR200c, miR141, miR429), miR34a, miR34b and miR203a are considered to play important roles in tumor cell migration by the regulation of ZEB1 and CDH1." (PMID 33419253, 2020). "ZEB1, as a transcription factor, promotes tumor invasion and metastasis by inducing EMT in many cancers." (PMID 31952541, 2020). "On the other hand, miR-200c in TNBC models strongly inhibited tumour growth and impaired tumour cell–mediated vascularization, by inhibiting PDGFRß activity in vascular lacunae and acting on ZEB1, one of the main transcriptional factors in EMT induction." (PMID 32188472, 2020). "Wnt/β-catenin signaling pathway can promote EMT through ZEB1 up-regulation to elevate the invasion and malignancy of tumor cells." (PMID 32664703, 2020). "The EMT transcription factor ZEB1 has multiple functions and if it is acting as a transcriptional repressor or activator strongly depends on the tumor type." (PMID 32094334, 2020). "Based on these data, we can conclude that alteration of the balance between AGR2 and ZEB1 in favor of ZEB1 leads to the acquisition of an aggressive and more invasive phenotype of tumor cells." (PMID 32570918, 2020). "Further analysis showed that the percentage of cells co-expressing LGR5 and ALDH1, LGR5 and OCT4, and LGR5 and ZEB1 in tumor-like structures formed by LGR5+ AM epithelial cells was significantly higher than that in those formed by parental AM epithelial cells." (PMID 32382005, 2020). "In agreement with this transition, we observed hypo-methylation of ZEB1 during tumor development in KSHV infected cells." (PMID 32603362, 2020). "IHC staining of CD44 and EMT-related markers (Twist, ZEB1 and E-cad) in tumor tissues was implemented." (PMID 32497020, 2020). "ZEB1 has been shown to be strongly associated with this complex process, wherein EMT-like stromal cells possessing high ZEB1 levels trigger the tumor-budding phenotype by tumor-stroma crosstalk." (PMID 32266287, 2020). "By the large, above results provided strong evidence that miR-4269 functioned as a tumor suppressor in PC progression via suppression of ZEB1-regulated OTX1." (PMID 32484209, 2020). "In turn, upregulation of Zeb1 in tumor cells increases VEGFA production and reciprocally induces endothelial Jag1 to create a positive feedback loop." (PMID 33046710, 2020). "Intriguingly, we find that different from the exclusive basal expression of Zeb1 in wild-type prostate, Zeb1+ epithelial cells can be detected in the luminal compartment in Hi-Myc mice or in human prostate hyperplastic or tumor samples." (PMID 32024836, 2020). "To explore the molecular mechanism by which miR-128 regulates anti-tumor immunity, we detected the regulation of miR-128 to ZEB1." (PMID 32536914, 2020). "These upstream mediators induce and enhance the expression of ZEB1 and -2 through sponging their target miRs, resulting in an increase in malignancy and invasion of tumor cells." (PMID 32664703, 2020).
tumor (continued). "Mir-190 is an efficient tumour suppressor that limits angiogenesis; the ZEB1-miR-190-SMAD2 interaction participates in TGF-β and VEGF regulation in humans." (PMID 33391272, 2020). "ZEB1 is inappropriately upregulated in a variety of malignant tumor types and functions as a stimulating factor of tumor invasion and metastasis." (PMID 31974363, 2020). "Secondly, several previous researches have demonstrated the interplay between ZEB1 and AR signaling in various tumor types 9,20,21." (PMID 32153739, 2020). "By suppressing Akt/mTOR signaling pathway, miR-708 acts as an anti-tumor agent to inhibit ZEB1, leading to the suppressing EMT mechanism." (PMID 32664703, 2020). "Consistently, we detected an increase in Zeb1+ basal cells and emergence of Zeb1+ p63− or Zeb1+ CK5− cells in prostates of both tumor models." (PMID 32024836, 2020). "Accordingly, in a SMAD4/7 knock-out mouse model, SMAD4 was required for tumor formation, and a low level of SMAD7 expression promoted an invasive phenotype and metastatic spread associated with ZEB2/ZEB1 switching." (PMID 32759677, 2020). "EMT transcriptional factors, Snail/Slug, Twist1 and ZEB1, are pivotal in regulation of tumor metastasis and stemness." (PMID 32549341, 2020). "We considered samples to be positive for ZEB1 when nuclear expression was observed in more than 5% of tumor cells." (PMID 32106476, 2020). "Our previous work additionally evidenced a prominent role of EMT transcription factors ZEB1 and Snail in the regulation of TF expression in tumor cells." (PMID 32152404, 2020). "In PDAC, tumor-budding cells and adjacent stromal cells showed increased levels of the E-cadherin repressors ZEB1, ZEB2, and SNAIL1." (PMID 32781778, 2020). "MALAT1 in turn induces ZEB1 through miR-204 down-regulation to enhance the malignancy and invasion of tumor cells via EMT induction." (PMID 32664703, 2020). "As one of the major inducers of EMT, ZEB1 represents an important molecule that plays a crucial role in tumor progression and metastasis and the expression of which correlates with poor clinical outcome in cancer patients." (PMID 32266287, 2020). "Recently, expression of ZEB1 activates signaling pathways leading to enhanced cell proliferation, and tumor growth." (PMID 32309226, 2020). "The expression profile of ZEB1 in 60 fresh GC and adjacent non-tumor tissues and 50 normal gastric specimens was assessed by qRT-PCR, and the association of ZEB1 expression with clinicopathological features was investigated." (PMID 32153739, 2020). "In turn, ectopic Zeb1 in tumor cells increases VEGFA production and reciprocally induces endothelial Jag1 in a paracrine manner." (PMID 33046710, 2020). "MiRs are able to act as onco-suppressor factors and inhibit the malignancy of tumor cells through ZEB1/2 down-regulation." (PMID 32664703, 2020). "Conversely, in the same tumor, CT increased ZEB-1 and CD90 levels while the combined treatment with Pep R reverted the expression of the mesenchymal markers." (PMID 32708431, 2020). "Our study unveiled that miR-4269 exerted its tumor inhibitory effects on PC progression by modulation of ZEB1/OTX1 axis, which offered a new insight into the clinical treatment of PC patients." (PMID 32484209, 2020). "Mouse TAMs that expressed Zeb1 were prone to the polarization toward an F4/80low pro-tumor phenotype and accelerated tumor growth." (PMID 33194645, 2020). "In this study, we uncovered a novel mechanism of promotion of anti-tumor immunity by miR-128 through regulating the ZEB1/CD47 axis, thus linking an EMT regulatory program to anti-tumor immunity in PDAC." (PMID 32536914, 2020).
tumor (continued). "LncRNA TP73-AS1 reduces the expression of miR-200a to up-regulate ZEB1, leading to the enhanced progression and malignancy of tumor cells." (PMID 32664703, 2020). "The expression of miR-200c-3p in exosome potentially reduces the tumor-driving function of exosome, which is probably mediated by ZEB-1 protein." (PMID 32600257, 2020). "Zinc finger E-box binding homeobox 1 (Zeb1), a transcription factor that facilitates tumor invasion by augmenting EMT in carcinoma cells, represents a unique obstacle to cancer therapeutics." (PMID 32566256, 2020). "Mechanistically, the tumor suppressive properties of miR-4269 in PC were mediated by ZEB1/OTX1 pathway." (PMID 32484209, 2020). "MALAT1 was found to enhance the expression of ZEB1 through miR-143-3p down-regulation, resulting in elevated migration and metastasis of tumor cells." (PMID 32664703, 2020). "As evidence confirmed in pancreatic cancer, the APA of ZEB1 rapidly responds to genotoxic stress and promotes gene expression, thereby improving the adaptability of tumor cells in a flexible tumor microenvironment." (PMID 32626751, 2020). "Transcriptional repression of E-cad (hallmark of malignant tumours) is mediated by EMT-TFs, including ZEB1 and ZEB2, the Snai1 family (Snail, Slug, and Smuc) and basic helix-loop helix factors (Twist and E12/E47)." (PMID 33207810, 2020). "It was demonstrated that ZEB1 gene expression in GC tissues is higher than adjacent non-tumor or normal gastric tissues." (PMID 32153739, 2020). "Here, we showed that loss of PER2 enhanced tumor invasion by activating transcriptional genes of EMT, including TWIST1/2, ZEB1/2, and MMP1, suggesting a wide-range influence of PER2 on EMT process." (PMID 32185221, 2020). "The results indicated that cells exhibiting loss of Zeb1 expression showed significantly reduced adhesion to a HUVEC monolayer and a decreased rate of tumor cell transmigration compared with shCtrl/231 cells." (PMID 33046710, 2020). "Our group and other researchers find that ZEB1 is an oncogenic factor in promoting tumor cell proliferation, migration, and invasion." (PMID 32620870, 2020). "In the next step, expression level of stemness relatedgenes (OCT4, SOX2, KLF4, c-MYC and NANOG) and EMTtranscription factors (CDH1, CDH2, SNAIL1, TWIST1,TWIST2 and ZEB1) were evaluated in all tumor samples andmammospheres." (PMID 31376329, 2020). "Ectopic overexpression of miR-200c in the CD117+/CD44+ cells inhibited EMT and induced tumor suppression by directly repressing ZEB1 and Vimentin, which resulted in a subsequent upregulation of the E-cadherin expression." (PMID 32850313, 2020). "Of note, ZEB1 is upregulated in cancer and tumor microenvironment cells but its downregulation to around half of the original upregulated levels is sufficient to block tumor progression." (PMID 30910999, 2019). "The miR‐200 family was found to act as a tumor‐suppressive group of miRNAs that targets ZEB1, ZEB2, and Slug genes, which drive epithelial–mesenchymal-transition and tumor progression in prostate cancer cells." (PMID 31866857, 2019). "The Ehi and E/M tumor cells were also consistently demonstrated by another set of anti–E-cad and anti-ZEB1 antibodies." (PMID 31331982, 2019). "While opposite effects of ZEB1 and miR-101-3p in CC whereby ZEB1 functions as an oncogene, and miR-101-3p as a tumor suppressor have also been demonstrated, their direct interaction in CC has not yet studied." (PMID 31092700, 2019). "Previous studies demonstrated the pro-tumour effect of ZEB1 by revealing its stimulatory effect on EMT32." (PMID 31263103, 2019). "PRMT1 expression in tumor tissue was compared to the IHC expression of EMT-related transcription factors (ZEB1, RUNX1, and TWIST1) and cell surface markers (ß-catenin, N- and E-cadherin)." (PMID 31655611, 2019).